MMP2 (matrix metallopeptidase 2)
Diseases named in the same sentence as MMP2 in open-access papers (continued):
Sharing a sentence is not in itself a finding about the gene and the disease.
endometriosis (continued). "Women with endometriosis showed significantly reduced level of active MMP-2 in eutopic endometrium as compared to women without endometriosis." (PMID 27695098, 2016). "Furthermore, a significant reduction of lesion numbers was observed upon inhibition of MMP-2 and COX-2 in mouse model of endometriosis." (PMID 27695098, 2016). "The present study documents reduced MMP-2 activities in uterine endometrium of the endometriosis patients than the women without endometriosis." (PMID 27695098, 2016). "For example, the expression levels of MMP-2 and MMP-9 were higher in women with endometriosis." (PMID 23843796, 2013). "In addition, MMP-2 and MMP-9 are elevated in the urine of patients with endometriosis compared to control." (PMID 23843796, 2013). "Here, we showed that CAPN 7 promotes hESC migration and invasion by increasing the activity of MMP-2; thus, it is plausible to speculate that CAPN 7 might play an important role in endometriosis." (PMID 23855590, 2013). "Matrix metalloproteinase 2 (MMP-2) has been reported to be an important regulator of cell migration and invasion through degradation of the extracellular matrix (ECM) in many diseases, such as cancer and endometriosis." (PMID 23855590, 2013). "Thus, we may suppose that MMP-2 and MMP-9 are less suppressed in endometriosis patients, which, in turn, can lead to active migration (cell invasion)." (PMID 38255200, 2024). "Specifically, the mechanism of action of MMP-2 and MMP-9 involves the degradation of the extracellular matrix (ECM), which facilitates the infiltration and attachment of endometrial cells to neighboring tissues, ultimately resulting in the development of endometriosis lesions." (PMID 38398530, 2024). "Additionally, certain genes that regulate MMP-2, MMP-9, and TGF-β1 may contribute to the elevated expression of these enzymes in endometriosis." (PMID 38398530, 2024). "Moreover, we also detected the serum levels of proteins associated with cell proliferation, angiogenesis, and epithelial-mesenchymal transition processes which are closely related to the pathogenesis of endometriosis, such as VEGF, MMP-2 and MMP-9,21–23, by ELISA." (PMID 31727934, 2019). "Previous studies reported that MMP2 expression is increased along with other proteases in the late secretory endometrium, and that the expression level of MMP9 is elevated in patients with endometriosis, suggesting that their endometrial tissue is inherently more invasive." (PMID 31324015, 2019). "Recent studies reported that matrix metalloproteinase-2 (MMP-2), MMP-9, tissue inhibitor of matrix metalloproteinases (TIMP-1) and transforming growth factor-β2 (TGF-β2) express a tendency to higher gene expression in the eutopic endometrium of women with endometriosis." (PMID 28174513, 2017). "Also, the expression of MMP-2 was significantly elevated in advanced endometriosis (stages III and IV according to the revised classification of the American Fertility Society), indicating that MMP-2 may be responsible for the development of endometriosis." (PMID 24294950, 2013). "Studies have shown increased activity of MMP-2 and MMP-9 in the endometrial tissue of women with endometriosis compared to that of women without endometriosis." (PMID 40429279, 2025). "We applied the quantitative polymerase chain reaction and the immunofluorescence method to investigate KISS1, its receptor (KISS1R), MMP-2, and MMP-9 in the eutopic and ectopic endometrium in women with and without endometriosis." (PMID 38255200, 2024). "Recently, a higher mRNA expression of MMP2 and MMP9 was detected in menstrual blood-derived stromal cells from women with endometriosis compared to patients without endometriosis." (PMID 37893104, 2023). "The aim of the study was to evaluate the level of MMP-2 and MMP-9 expression in the ectopic endometrium of women with visible endometriotic lesions and eutopic endometrium in patients with no signs of endometriosis." (PMID 33072202, 2020).
endometriosis (continued). "Our study demonstrates a statistically higher expression of MMP-2 and MMP-9 both in ectopic and eutopic endometrium samples compared to samples taken from patients without endometriosis." (PMID 33072202, 2020). "Several studies have reported higher expression of MMP-2, MMP-9, MMP-14, and MMP-24 in the eutopic endometrium or ectopic lesions of women with endometriosis, as compared to levels in women without endometriosis." (PMID 31636643, 2019). "Although patients with endometriosis were reported to have elevated PGE2 levels, the effect of PGE2 on MMP-2 is still not well investigated." (PMID 27695098, 2016). "The aim of the study was to evaluate the level of MMP-2 and MMP-9 expression in ectopic and eutopic endometrium of women with visible endometriotic lesions and eutopic endometrium in patients with no signs of endometriosis." (PMID 33072202, 2020). "During the menstrual phase, the examination of MMP expression in menstrual serum was conducted by Malik (2006), who investigated MMP-2 and MMP-9 by zymography and showed that the expression of the latent and the active forms of MMP-9 were similar in women with endometriosis and in those without." (PMID 32498419, 2020).
Obesity (70 papers, 2011 to 2026). Accumulation of substantial excess body fat. "In the present study, we found obesity-specific associations of MMP gene polymorphic loci with BC: c.-1306 C > T (rs243865) MMP2, and c." (PMID 36289879, 2022). "For MMP-2 polymorphism, similar results have been observed, with CC genotypes being more common in subjects (controls and children with obesity) with higher MMP-2 concentrations, while CT genotypes and the T allele are less common in children with obesity." (PMID 36499740, 2022). "Results showed that obesity worsened heart function and this was associated with MMP-2 upregulation, MMP-28 downregulation, and inhibition of superoxide dismutases (SODs)." (PMID 33923282, 2021). "MMP-2 was described as elevated at circulating level in obese humans, and furthermore, it has been implicated in leptin resistance causing IR and obesity in mice by leptin receptor cleavage." (PMID 32214011, 2020). "It has been demonstrated that the inflammatory profile associated with obesity contributes to pro-inflammatory cytokines that stimulate MMP-2 synthesis and activation, which compromise the lean mass and physiological function of obese rats." (PMID 29593554, 2018). "We undertook an association analysis of 3 functional polymorphisms in the promoter of the MMP-2 gene (-1306C/T, -1575G/A and -790T/G), to investigate the possible role for MMP-2 as a genetic risk factor for obesity (in terms of increased PBF) in the ABC study." (PMID 21777433, 2011). "Genetic variation in MMP-2 has been previously investigated for association with obesity, in adults from Korea." (PMID 21777433, 2011). "Interestingly, polymorphisms in the MMP2 gene were associated with obesity in the Korean population." (PMID 37445827, 2023). "It is suggested that leptin receptor degradation is another mechanism of leptin resistance in obesity and aging, and it could be associated with increased activity of the matrix metalloproteinase-2 (Mmp-2)." (PMID 38068822, 2023). "In an independent study searching for sex-specific genetic associations of gene polymorphism with obesity and overweight, the frequency of the C/G genotype of the MMP2 variant rs1132896 was higher in weight gainer women than in stable weight women compared to the common G/G genotype." (PMID 37445827, 2023). "Furthermore, tissue degradation by MMP-2 is pivotal to inflammation, and obesity is associated with low grade inflammation." (PMID 21777433, 2011). "Taken together with our own results, it can be concluded that MMP-2 may be an important susceptibility gene for obesity in both children and adults." (PMID 21777433, 2011). "Regarding enzymes, several studies observed significantly higher levels of salivary alpha-amylase (sAA), matrix metalloproteinase-9 (MMP-9), and matrix metalloproteinase-2 (MMP-2) in individuals with obesity, those in the control group." (PMID 40153192, 2025). "Obesity, through mechanisms of chronic inflammation and endocrine disruption, exacerbates MMP-2 activity, while sedentary lifestyles further contribute to vascular dysfunction." (PMID 40311090, 2025). "In the group of women with obesity compared to those with normal body weight, significantly higher serum levels were found for IL-6, MMP-2, and resistin." (PMID 39769504, 2024). "By further functionalization using hyaluronic acid (HA) and MMP2 substrate‐linking P3 peptide‐modified HA (P3‐HA), an enhanced anti‐obesity effect is obtained by dual‐targeting of P3 and HA, and HA‐mediated CD44 poly‐clustering after MMP2 cleavage." (PMID 39324577, 2024). "Alternatively, in addition to the IGF/IGFBP/IGFALS ternary complex, MMP2 can cleave COL6A3 to generate endotrophin, which is associated with onset of obesity-related metabolic disorders." (PMID 38645061, 2024). "Resistin and MMP-2 were significantly different between women with obesity and women with normal body weight." (PMID 39769504, 2024).
Obesity (continued). "MMP2 has been shown to intervene in genetic models of obesity, using two well-studied models of genetic obesity, specifically in two well-studied models involving ob/ob and db/db mice." (PMID 37445827, 2023). "The present study demonstrated higher concentrations of MMP-2 in the saliva of subjects with obesity compared to individuals with normal body weight." (PMID 36835557, 2023). "It has been found that HFD-induced obesity stimulated Mmp-2 protein activation within the hypothalamus with subsequent cleavage of the extracellular domain of the leptin receptor." (PMID 38068822, 2023). "Compared to nonOB, three proteins were found in lower levels in OB individuals: the obesity-related adipokine adiponectin, the inflammatory proteins matrix metalloproteinase-2 (MMP-2) and osteocalcin." (PMID 36614270, 2023). "Our result also demonstrated that matrix metalloproteinase family members, MMP-2 and MMP-9, were potential targets of fucoidan against PFOA-associated obesity." (PMID 36034923, 2022). "By the study of molecular mechanisms underlying the effects of obesity development and possible actions of QCT in aged lean and obese ZDF rats we observed the potential role of MMP-2 and MMP-28." (PMID 33923282, 2021). "In conclusion, worsened heart function due to obesity involved changes in MMP-2 and MMP-28 and attenuation of antioxidant defense by SOD." (PMID 33923282, 2021). "Numerous studies demonstrated that ginseng and/or ginsenosides suppressed obesity and adipocyte inflammation by regulating several pathways, such as matrix metalloproteinases (MMP)-2 and MMP-9, AMPK signaling, and/or PPAR-γ signal pathways." (PMID 32630030, 2020). "In accordance with the current study, high levels of MMP2 were previously observed in individuals with obesity." (PMID 31590286, 2019). "In particular, the results observed in changes in circulating levels of MMP2 support the need for additional longitudinal studies to elucidate the role of this myokine as a protective factor against obesity." (PMID 31590286, 2019). "In contrast, plasma levels of MMP2 and irisin were higher in individuals with obesity than those with normal weight." (PMID 31590286, 2019). "The current study demonstrated that energy-restricted and surgical strategies of weight loss induced changes in levels of circulating myokines such as IL-6, IL-8, MMP2, and irisin in patients with obesity." (PMID 31590286, 2019). "High MMP-2 expression was observed in the adipose tissue of mice with nutritionally induced obesity as well as in genetically obese mice." (PMID 26599360, 2015). "Mmp2, 3, Mmp12 and Mmp13 are reportedly positively correlated with the degree of obesity and were up-regulated in the visceral WAT of HFD fed mice." (PMID 22947075, 2012). "Additional studies are now required to further investigate MMP-2 involvement in the development of obesity." (PMID 21777433, 2011). "High expression of MMP-2 has been demonstrated in adipose tissue of mice with nutritionally induced obesity, as well as in genetically obese mice." (PMID 21777433, 2011). "Several lines of evidence suggest a possible functional role of Matrix metalloproteinase -2 (MMP-2) in obesity." (PMID 21777433, 2011). "This study evaluated the therapeutic potential of lycopene in attenuating obesity-induced cardiac remodeling, based on its antioxidant and anti-inflammatory properties and its ability to inhibit matrix metalloproteinase-2 (MMP-2) activation, thereby preserving myocardial collagen integrity." (PMID 41588666, 2026). "Growing evidence also suggests that circulating MMP-2 and MMP-9 levels could serve as potential biomarkers of low-grade inflammation and cardiovascular risk in obesity." (PMID 41227041, 2025). "Reportedly, patients with obesity exhibit increased plasma levels of MMP-2 and -9." (PMID 36902320, 2023).
Obesity (continued). "Of the five MMP2 variants analyzed, two synonymous single nucleotide polymorphisms (SNPs), namely rs17242319 (Gly226Gly) (now called rs1132896 in the SNP database BUILD 129) and rs10775332 (Phe602Phe) were significantly associated with overweight/obesity." (PMID 37445827, 2023). "Patients with obesity reportedly exhibit an increase in both MMP-2 and -9 plasma levels." (PMID 36902320, 2023). "Since increased Cdc42 and MMP-2 activity are observed in obesity and aging, it is conceivable that increased Cdc42 activity may lead to the degradation of the leptin receptor and affect leptin transport to the brain." (PMID 38068822, 2023). "Obesity robustly induced transcription of fibrotic genes in both subcutaneous white AT (scWAT) and visceral white AT (vWAT), including Col1a1, Col6a1, and Mmp2, consistent with RNAseq analysis of adipocytes that acquire a fibroblast-like transcriptional signature in response to a HFD feeding." (PMID 36229481, 2022). "Obesity can increase blood MMP‐2 and ‐9 concentrations in humans." (PMID 33274549, 2021). "Other obesity‐associated factors such as leptin might have been better proxy measures of maternal obesity, since leptin can inhibit inflammation‐mediated MMP2 and MMP9 activation at least at term of pregnancy." (PMID 32614494, 2020). "We also observed that HT decreased the inflammatory induction of active players—and potential targets—of obesity-related remodeling, including the proteolytic enzyme MMP-2 (gelatinase A), the proangiogenic VEGF-A, as well as the pro-inflammatory enzyme COX-2 and its eicosanoid product PGE2." (PMID 31627295, 2019). "It has been reported that leptin, an obesity-related factor, upregulates MMP-2 and induces EMT." (PMID 28505114, 2017). "Furthermore, others have shown that some MMPs and their inhibitors (TIMPs) are modulated with obesity level in mice and in humans and that MMP2 and MMP9 are essential for adipocyte differentiation." (PMID 28409151, 2017). "Whilst a study examining obesity in adults demonstrated increased MMP-2 (and MMP-9) levels." (PMID 21777433, 2011). "This understanding may indicate that a reduction in the expression of MMP-2 and MMP-9 after bariatric surgery could be a marker of clinical improvement in obesity, since a reduction in serum MMP levels is associated with a control of extracellular matrix function in adipocytes." (PMID 39766340, 2024). "The results showed that the combination therapy was significantly more effective than either gemcitabine or MMP-2/9 inhibitor treatment alone for both non-obesity- and obesity-associated diabetic pancreatic cancer, resulting in the smallest tumor volume and lowest number of metastases (all p<0.05)." (PMID 33251135, 2020). "Although direct evidence remains limited, preliminary findings suggest that incretin-based pharmacotherapy reduces circulating MMP-2 and MMP-9 levels, highlighting its potential to restore ECM homeostasis and attenuate chronic inflammation in obesity." (PMID 41227041, 2025). "Matrix metalloproteinases (MMPs), especially MMP-2 and MMP-9, are key regulators of ECM remodeling and inflammation in obesity." (PMID 41227041, 2025). "One proposed mechanism for leptin resistance involves matrix metalloproteinase-2 (MMP-2), a proteolytic enzyme that becomes activated in the hypothalamus during obesity." (PMID 41226331, 2025). "Like SPARC and MMP-2, other myokines are involved in ECM remodeling, a process that is altered in muscle of people with obesity and T2D but improved by bariatric surgery." (PMID 40171198, 2025). "IL-6 is predominantly produced by infiltrated adipose tissue macrophages, while elevated MMP-2 and MMP-9 levels in obesity contribute to adipose tissue remodeling, triggering proinflammatory cytokine secretion and amplifying the inflammatory response." (PMID 38495901, 2024). "This showed that obesity is correlated with increased MMP expression in adipose tissue, with MMP-2 and MMP-9 being involved in the ECM remodeling process." (PMID 39766340, 2024).